BRD4 (bromodomain containing 4)
Diseases named in the same sentence as BRD4 in open-access papers (continued):
Sharing a sentence is not in itself a finding about the gene and the disease.
cancer (continued). "SEs driven by the BRD4/LSD1/NuRD complex significantly affect many well-characterized cellular signaling pathways essential for the growth, survival, and homeostasis of cancer cells." (PMID 37501079, 2023). "Bromodomain-containing protein 4 (BRD4), the major component of bromodomain and extra-terminal domain (BET) protein family, has important functions in early embryonic development and cancer development." (PMID 37737256, 2023). "- miR-766-5p decreases the MYC expression level in cancer cells.- Forced expression of miR-766-5p lead to inhibition of tumor growth by targeting CBP and BRD4." (PMID 37205191, 2023). "The PROTAC degrader ARV-825, which effectively degrades bromodomain-containing protein 4 (BRD4) via E3 ligase cereblon (CRBN)-mediated ubiquitination, exhibits potent efficacy against several cancer types, including PDAC." (PMID 38174069, 2023). "The excellent extrapolation of this generalized model to other cancer types for which fewer data are available provides confidence that the TFs IRF1, STAT1, NFKB, and BRD4 are in general dominant regulators of CD274 expression." (PMID 35289334, 2022). "This is in agreement with previous data showing that YAP regulates RNApol2 pausing and that in cancer cells, YAP-dependent transcription relies on BRD4 activity." (PMID 35871292, 2022). "A recent study revealed that inhibition of the BD1, but not the BD2, phenocopied the effects of BETi in suppressing cell proliferation and survival in cancer cell models, suggesting the essential role of the BD1 for the oncogenic function of BRD4." (PMID 36475791, 2022). "In BETi-resistant cancer cells, CDK1 upregulation and BRD4 hyperphosphorylation were observed, including triple-negative breast cancer (TNBC)." (PMID 35402244, 2022). "Accordingly, c-MYC- or N-MYC-driven cancer cells, including TNBC, are more sensitive to BRD4 inhibition." (PMID 36139513, 2022). "BRD4, a chromatin modifier frequently upregulated in a variety of neoplasms including hepatocellular cancer (HCC), promotes cancer cell growth by activating oncogenes through its interaction with acetylated histone tails of nucleosomes." (PMID 35399501, 2022). "JQ1 has been proven to be a first-in-class BETi, which can downregulate the transcription of multiple genes through targeting BRD4, such as MYC, IL7R, and E2F1 in different cancer cells." (PMID 36499487, 2022). "In cancer cells BRD4 inhibition suppresses super-enhancer and IFN-γ driven transcription of PD-L1 (CD274 gene) by preventing binding of BRD4 and IRF1 to its promoter and enhancer regions." (PMID 36139513, 2022). "Aberrant degradation of the BRD4 protein in cancer leads to resistance to BET inhibitors, so BRD4 is emerging as a promising anticancer therapeutic target." (PMID 36524001, 2022). "An emerging body of evidence is forming in the literature that implicates the role of enzymes such as BRD4 and DNMT1/DNMT3B as epigenetic drivers of cancer and epithelial to mesenchymal transition." (PMID 35143483, 2022). "BRD4 is a basis of CRPC cell migration and invasion through AHNAK (protein that potentiates metastasis in a variety of cancers) transcription." (PMID 35401196, 2022). "Bromodomain-containing protein 4 (BRD4) is the most widely studied BET member and is up-regulated in a broad spectrum of human cancers." (PMID 35453346, 2022). "We have demonstrated that dual and triple action TP-scaffold compounds show promising results as anti-cancer agents, and the first generation of BTK/PI3K/BRD4 inhibitors, such as SRX3262, was cytotoxic to MCL cells." (PMID 35031886, 2022). "As one of the most commonly used BRD4 inhibitors, JQ1 attenuates the recruitment of BRD4 to the promoters of genes related to inflammation and cancer." (PMID 35154163, 2022). "BRD4 and HSPB1 have been found to upregulate ferritinophagy, and BRD4 and HSPB1 are highly expressed in many cancer types." (PMID 36339539, 2022). "Therefore, BRD4 may work as a potential therapeutic target for drug-resistant cancers." (PMID 36157053, 2022).
cancer (continued). "Four family members of BRDs: BRD2, BRD3, BRD4 and BRDT, have been identified, and among them, the role of BRD4 in cancers is the most well studied." (PMID 36309482, 2022). "Bromodomain-containing protein 4 (BRD4), a member of the bromodomain and extraterminal (BET) family, is considered to be a major driver of cancer cell growth and a new target for cancer therapy." (PMID 35402244, 2022). "Studies in HR-proficient mouse models of cancer show that BET inhibition, specifically targeting of BRD2 and BRD4, sensitizes tumors to PARPi by suppressing RAD51 transcription." (PMID 34572943, 2021). "De-ubiquitinase DUB3 binds to BRD4, but not BRD2/3, via a specific C-terminal motif (CTM), antagonizes SPOP-mediated BRD4 ubiquitination, and promotes BRD4 de-ubiquitination and stabilization, leading to BET-BD inhibitor resistance in cancer cells." (PMID 34540900, 2021). "It has been suggested that BRD4 inhibitor (+)-JQ1, enhanced BRD4 DNA methylation to induce ferritinophagy and ferrroptosis in cancer cells." (PMID 34226536, 2021). "In nuclear protein in testis (NUT) midline carcinoma (NMC), BRD3 and BRD4 fuse with NUT and retain it in the nucleus, which interferes with the differentiation of epithelial cells and promotes cancer growth." (PMID 34540687, 2021). "BRD4 is one of the widely studied and important BET proteins in cancer and is generally considered as an epigenetic reader that activated RNA polymerase II to combine active chromatin markers with transcriptional elongation." (PMID 34733788, 2021). "JQ1, a small molecule inhibitor that blocks BRD4 and c-MYC expression and promotes apoptosis, was recently reported to suppress cancer cell invasion and migration as well as tumor metastasis 13,14." (PMID 34803511, 2021). "The expression of ISX, BRD4, and PCAF mRNA in HCC cells and cells from cancer patients was quantified using an SYBR Green Quantitative RT–PCR kit (Invitrogen)." (PMID 34173348, 2021). "Although various BET inhibitors are undergoing clinical trials for the treatment of cancer and inflammatory diseases, it has to be noted that BET inhibitors target all BET family proteins, including Brd2, Brd3, and Brd4." (PMID 33830083, 2021). "Cancer cell metabolism is modified by alternative splicing of pyruvate kinase M1/2 (PKM) and bromodomain-containing 4 (BRD4) genes." (PMID 34771719, 2021). "BRD4, member of the Bromodomain and Extraterminal (BET) protein family, is largely acknowledged in cancer for its role in super-enhancers organization and oncogenes expression regulation." (PMID 34400879, 2021). "Brd4 belongs to the bromodomain extra terminal (BET) family and has emerged as an important epigenetic regulator in inflammatory gene expression and cancer development." (PMID 33830083, 2021). "Plasmacytoma variant translocation 1 (PVT1) is a long non-coding RNA (lncRNA) that functions as an oncogene in many cancers and is known to promote MYC expression in I-BET151-resistant AML cells in a BRD4-independent manner." (PMID 34540687, 2021). "Inhibition of BRD4 by (+)-JQ1, inhibit histone methyltransferase G9a or enhance the histone deacetylase SIRT1 to inhibit BRD4, downregulate GPx4, SLC7A11, SLC3A2 gene expression, regulate ferritinophagy, and induce ferrroptosis in cancer cells." (PMID 34226536, 2021). "BRD4 is one of the members of the bromodomain and extraterminal domain (BET) family, which is an essential epigenetic regulator of gene transcription and cancer development." (PMID 34956562, 2021). "Mechanistically, we find that bromodomain-containing protein 4 (BRD4) recruits Mediators and NF-κB p65 to form SEs at cancer stemness genes such as TP63, MET and FOSL1, in addition to oncogenic transcripts." (PMID 34172737, 2021). "In mammalian/cancer cells, YAP/TAZ-driven transcription is facilitated by binding to BRD4, a member of the bromodomain and extraterminal (BET) protein family of epigenetic modifiers that mediates interaction between enhancer sequences and associated promoters." (PMID 33913810, 2021).
cancer (continued). "Bromodomain-containing protein 4 (BRD4) is a part of the gene super-enhancer regions’ transcriptional machinery and governs the expression of many genes that are critical for cancer progress." (PMID 34834420, 2021). "Here the authors unravel a mechanism by which CAFs activate BRD4 and induce resistance to BET inhibitors in cancer cells through IL6/IL8 signaling." (PMID 34290255, 2021). "BRD4, a Bromodomain and Extraterminal (BET) protein family member, is a promising anti-cancer drug target." (PMID 34290255, 2021). "BRD4 amplification was reported to transcriptionally activate c-MYC 9,10, with the consequent promotion of cancer growth, invasion and metastasis 11,12." (PMID 34803511, 2021). "A combined therapy through inhibiting BRD4 and PI3K by a single molecule has been shown to produce potent antitumor effects in several cancer models driven by MYC13–15." (PMID 32694708, 2020). "As silencing of BRD4 downregulates the expression of the MYC (v-Myc Myelocytomatosis Viral Oncogene Homolog) oncogene, JQ1 is a potent anti-cancer molecule." (PMID 32414180, 2020). "In cancer stem cells, several studies mentioned that targeting BRD2 and BRD4 inhibited GIC proliferation and BRD4‐depleted induced GIC apoptosis." (PMID 33135348, 2020). "Therefore, BRD4 may serve as a tumor suppressor in these cancers." (PMID 32099528, 2020). "Despite the broad presence of BET proteins across thousands of enhancers, inhibition of these proteins (for instance the inhibition of BRD4 by the BET-bromodomain inhibitor JQ1), has led to specific targeting in multiple cancers, revealing cancer dependencies." (PMID 32634370, 2020). "NUT can fuse with the bromodomain BRD4 forming the oncoprotein BRD4-NUT, which plays an important role in the differentiation and proliferation of cancer cells." (PMID 32582706, 2020). "Significant differences in tumor sizes, metastases, and cancer stages were observed between patients with high and low levels of ISX or BRD4 expression." (PMID 31908141, 2020). "We further demonstrate that concurrent disruption of the acetyllysine binding function of BRD4 and the kinase activities of PI3K and CDK4/6 by the TP inhibitor improves efficacy in several cancer models." (PMID 32694708, 2020). "Therefore, inhibiting BRD4-NUT oncogenic function directly by BET inhibitors represents an attractive therapeutic approach but toxicity may limit the use of pan-BET inhibitors treating this cancer." (PMID 32366905, 2020). "Although treatment of BRD4 overexpressing tumors with BET inhibitors was shown to suppress the growth, yet, some of the cancer cells develop resistance eventually through different mechanisms." (PMID 33488950, 2020). "As a small-molecule inhibitor of BRD4, JQ1 has potent chemotherapeutic activity against various human cancers." (PMID 32157097, 2020). "We observed that CDK9 and BRD4 inhibition reduced butyrate-triggered NCOA4 expression, decreased Erastin, RSL3 and butyrate-induced cell death; in contrast, BRD4 inhibition by JQ1 triggered ferritinophagy and ferroptosis in cancer cells." (PMID 33298848, 2020). "BRD4 inhibitors, such as JQ1, have exerted efficacious anti‐proliferation activities in diverse cancers." (PMID 32954665, 2020). "In this study, we describe the first in class rationally-designed triple activity inhibitor that concomitantly disrupts functions of three critical targets based upon known synthetic lethality relationships in cancer cells—CDK4/6, PI3K, and BRD4." (PMID 32793389, 2020). "Nonetheless, all these results suggest that BRD4 regulates HIF target genes through various mechanisms and BRD4 inhibition can also be used to modulate HIF activity to treat cancer." (PMID 32286255, 2020). "Higher BRD4 expression was significantly related to poor prognosis in HCC patients, and BRD4 intensity in cancer tissues was an independent prognostic factor for OS." (PMID 32927435, 2020).
cancer (continued). "In conclusion, in this study we report the first triple action single-molecule inhibitor SRX3177, which disrupts cancer cell signaling through simultaneously inhibiting CDK4/6, PI3K, and BRD4." (PMID 32793389, 2020). "BRD4 is the most cancer‐related BET family member, and studies have revealed important roles for BRD4 protein in certain types of cancer." (PMID 32175692, 2020). "Dysregulated BRD4 and other BET proteins are frequently found in cancer showing aberrant chromatin remodeling and gene expression." (PMID 32404196, 2020). "While blocking BRD4 interaction with acetylated histones using BET inhibitors (BETis) has been tested in clinical trials, many cancers have acquired BETi resistance." (PMID 32575711, 2020). "Inhibition of BRD4 and other proteins of the BET family by BET inhibitors was considered to be a new strategy for cancer treatment." (PMID 32954665, 2020). "Inhibition of BRD4 attenuates a replication stress response and impairs HR repair, providing a rationale for combination of BET inhibitor with drugs targeting DDR for cancer treatment." (PMID 31480716, 2019). "Recently, several studies have shown that various transcriptional factors, such as STAT1, STAT3, BRD4, NF-kB, PI3K/AKT/mTOR, and MEK1/2/ERK1/2, promoted PD-L1 transcription in cancer cells." (PMID 31818309, 2019). "For example, the BRD proteins BRD9, BRD4, and ATAD2 were focally amplified in multiple cancer types and their increased copy numbers were significantly, positively correlated with higher mRNA expression levels." (PMID 30760718, 2019). "Therefore, BRD4-specific inhibitors might be a better choice for cancer treatment." (PMID 31523195, 2019). "BRD4, a member of the BET (Bromodomain and extraterminal domain) family, is a transcriptional regulator in mitotic cells and plays a crucial role in cancers." (PMID 30784214, 2019). "Among the recurrent genomic events, those in BRD9, EP300, ATAD2, HDAC4, PRBM1, BRD4, and BRD1 were observed in the highest numbers of cancer types (nine, eight, eight, eight, seven, seven, and seven, respectively)." (PMID 30760718, 2019). "Finally, it is worth noting that diverse types of cancer cells are “addicted” to high BRD4 levels to maintain a pro-proliferative transcriptional program, which could negatively impact the expression levels of BRD2 and BRD3, which in the case of BRD3 could contribute to increased proliferation." (PMID 30554943, 2019). "Small molecules targeting bromodomains of BRD4 and other BET family proteins display strong anti-tumor activities, suppressing the proliferation and transformation potential of various cancer cells." (PMID 29434197, 2018). "Recent studies suggest that pharmacological targeting BRD4, a member of the BET bromodomain family, can indirectly suppress MYC expression in various cancer models." (PMID 29445162, 2018). "BRD4, member of the Bromodomain and Extraterminal (BET) protein family, is largely acknowledged in cancer for its role in super-enhancers (SEs) organization and oncogenes expression regulation." (PMID 30466442, 2018). "The decreased amount of BRD4 expression results in reduced activity of MYC oncogene, which is a potential therapeutic target in different cancer studies." (PMID 29941841, 2018). "In both assays, BRD4 inhibition by JQ1 powerfully blocked HUVEC proliferation induced by VEGF, consistent with its effect on many cancer cell lines." (PMID 28851877, 2017). "Clinical trials using inhibitors against BRD4 and MLL1 in cancer are still underway and, if successful, will be interesting to determine if attenuation of the protumorigenic effects of senescent cells is part of the success, such as inhibition of the SASP." (PMID 29186801, 2017). "Our study provides strong rationale for clinical investigation of this combination especially in women whose cancers overexpress both CHK1 and BRD4." (PMID 28881656, 2017). "BRD4, mTOR, IL-1α and additional regulators of SASP are potential targets for anti cancer treatment." (PMID 28966805, 2017).
cancer (continued). "JQ1 showed selectivity for the BET family, with higher affinity for Bromodomain-Containing Protein 4 (BRD4) and demonstrated anti-tumor activity in several cancer cell types." (PMID 27651838, 2016). "To test that idea, we investigated the role of BRD4 in HCC and the anti-cancer effects of BRD4 inhibitors in HCC." (PMID 26575167, 2016). "The published data indicate that BRD4 and its recruitment of P-TEFb to the MYC promoter region play a particularly important role in MYC expression in human cancer cells." (PMID 26083714, 2015). "Two other chromatin regulators, the chromatin reader Brd4 and histone acetyltransferase YEATS4, were also highly ranked as putative cancer driver genes." (PMID 24874471, 2014). "Here we will discuss the current knowledge on Brd4 and HEXIM1 and their implication as novel therapeutic options against cancer." (PMID 24592384, 2014). "The cancer driver signatures for SETDB1, YEATS4, NSD3, and BRD4 in TCGA datasets suggests that these genes are important cancer therapeutic targets and potential patient tailoring markers for epigenetics drug discovery efforts." (PMID 24874471, 2014). "Brd4, an epigenetic regulator of MYC, has been identified as a promising drug target for MYC-driven cancer." (PMID 25495526, 2014). "In this review, we will focus on the recent findings on Brd4/HEXIM1 with respect to their newly discovered roles in cell cycle progression and cancer." (PMID 24592384, 2014). "Involvement of Brd4 and HEXIM1 in tumorigenesis through the P-TEFb-dependent and -independent mechanisms opens a new and exciting venue for cancer research." (PMID 24592384, 2014). "Inhibition of the BRD4 protein by JQ1, thus, proved to have effective antitumoral properties, suggesting that targeting MYC expression is feasible in selected cancers." (PMID 24231268, 2013). "A BRD4 degrader (ZBC260) achieved potent BRD4 depletion at low nanomolar doses, suppressed FOXM1/MYC and HR gene expression, enhanced PARP1 trapping, and produced strong synergy with olaparib, including in patient-derived cancer cells." (PMID 41820523, 2026). "Preclinical data also support the use of bromodomain inhibitors targeting bromodomain protein BRD4 in cancers lacking PRC2 function, as well as for its involvement in MEK inhibitor resistance." (PMID 41374983, 2025). "Therefore, inhibition of BET family proteins, including BRD2, BRD3, BRD4, and BRDT, represents a promising epigenetic approach for various cancer treatments." (PMID 40937321, 2025). "Separately, BRD2/BRD4 affects oncogenes, including MYC, related to cancer." (PMID 40937321, 2025). "Indeed, published work indicates that the inhibition of BRD4, GAB2, or IRS2 restrains the progression of several types of cancer." (PMID 40285526, 2025). "Whether CHMP5 also regulates the BRD4-p300-MYC axis and super-enhancers in these cancers remains to be determined." (PMID 40319015, 2025). "dBET1 induces the degradation of BRD4, suppressing MYC expression and apoptosis in cancer cells." (PMID 39851497, 2025). "Bromodomain-containing protein 4 (BRD4), a member of the BET family, affects cell cycle progression by activating oncogenes such as c-MYC, JUNB, CCND1 and CCNA1, thereby selectively interfering with mediating cancer cell growth and escaping apoptosis." (PMID 40078291, 2025). "Thus, disrupting the interaction of BRD4 with di-acetylated TWIST can suppress tumorigenesis by suppression of invasion, cancer stem cell-like proprieties, and malignancy of BLBC cells." (PMID 39942749, 2025). "BRD4 reduces MHC I expression and antigen processing in the context of cancer, and BRD4 activity may promote tumor progression by increasing chemokine-mediated recruitment of myeloid cells to the tumor." (PMID 40762981, 2025). "Suppression of BRD4-bound enhancers resulted in decreased cell viability, suggesting that exploiting H3K27ac provides CACNA2D1 with a cancer cell growth advantage and therefore promotes cancer progression." (PMID 40429844, 2025).